ZFAS1 (ZNFX1 antisense RNA 1)
Diseases named in the same sentence as ZFAS1 in open-access papers (continued):
Sharing a sentence is not in itself a finding about the gene and the disease.
gastric cancer (51 papers, 2016 to 2026). A primary or metastatic malignant neoplasm involving the stomach. "The overexpression of ZFAS1 leads to the loss of control of the cell cycle process, which in turn promotes the proliferation and migration of gastric cancer cells." (PMID 34134612, 2021). "The knockdown of ZFAS1 causes increase in gastric cancer sensitivity to paclitaxel by suppressing the NKD2 leading to induction of Wnt negative regulator, thus leading to the induction of Wnt/Β-Catenin pathway." (PMID 35582574, 2019). "To assess the role of ZFAS1 in gastric cancer cells phenotype, we performed loss-of-function and gain-of-function assays." (PMID 27246976, 2017). "Here, we reported that ZFAS1 expression is also overexpressed in gastric cancer, and its increased level is associated with poor prognosis and shorter survival." (PMID 27246976, 2017). "For instance, ZFAS1 is found to be overexpressed in gastric cancer and the increased level is associated with poor prognosis, besides, the oncogenic function is partly dependent on repressing KLF2 and NKD2." (PMID 29262629, 2017). "Elevated levels of ZFAS1 were detected in serum exosomes of gastric carcinoma patients, with high exosomal levels associated with lymph node metastasis and advanced TNM stage." (PMID 28430163, 2017). "For instance, the deficiency of ZFAS1 could weaken the aggression of gastric cancer cells by suppressing Wnt/β-catenin signaling pathway." (PMID 32744323, 2020). "In conclusion, our study showed for the first time that lncRNA ZFAS1 expression is up-regulated in gastric cancer tissues and cells, and its overexpression is associated with poor prognosis and may be a negative prognostic factor for gastric cancer patients." (PMID 27246976, 2017). "Moreover, in vitro and in vivo loss- and gain-of function assays were performed to investigate the roles of ZFAS1 on regulating gastric cancer cell phenotypes, and mechanism investigations document by which mechanism ZFAS1 regulating its underlying targets." (PMID 27246976, 2017). "We have recently reported that ZFAS1 is upregulated in gastric cancer and its expression level was associated with GC progression." (PMID 29970131, 2018). "Exosomal transfer mechanisms reveal ZFAS1's capacity to activate ERK signaling in gastric cancer cells, driving EMT and metastatic niche formation." (PMID 41450817, 2026). "lncRNA ZFAS1 is significantly overexpressed in several human malignant tumors, including colorectal, hepatocellular, and gastric cancers, and knockdown of ZFAS1 inhibits cancer cell proliferation and migration and increases apoptosis." (PMID 39006762, 2024). "In patients with gastric cancer, lncRNA ZFAS1 levels were found to be enriched in patients with gastric adenocarcinoma compared to healthy controls." (PMID 39682778, 2024). "The zinc finger antisense 1 (ZFAS1) is another lncRNA demonstrating oncogenic activity in gastric cancer." (PMID 38542354, 2024). "ZFAS1 is elevated in different types of cancer, like colorectal, colon, osteosarcoma, and gastric cancer." (PMID 38856786, 2024). "On the contrary, overexpression of ZFAS1 promoted the proliferation and migration of gastric cancer cells." (PMID 35089117, 2022). "LncRNA-ZFAS1 expression is increased in gastric cancer cells, and higher ZFAS1 has been correlated with lymph node metastasis and with tumour node metastasis (TNM) stages." (PMID 33081785, 2020). "In gastric cancer, ZFAS1 simultaneously interacted with EZH2 and LSD1/CoREST to inhibit KLF2 and NKD2 transcription to exert its oncogenic effects." (PMID 33202381, 2020). "Knockdown of ZFAS1 suppressed cancer cells proliferation and promoted cancer cells apoptosis in vitro, and restrained tumourigenesis of gastric cancer cells in vivo." (PMID 30288832, 2019). "ZFAS1 is able to regulate gastric cancer sensitivity by decreasing NKD2 and activating the Wnt/Β-Catenin pathway." (PMID 35582574, 2019).
gastric cancer (continued). "LncRNA-zinc finger antisense 1 (ZFAS1) has been shown to regulate gastric cancer cells sensitivity to cis-platinum." (PMID 35582574, 2019). "Increased expression of ZFAS1 in gastric cancer was also closely interrelated with TNM stage, lymph‐node metastasis, and tumour size." (PMID 30288832, 2019). "In gastric cancer, exosomal lncRNA ZFAS1 (ZNFX1 antisense RNA 1) promoted the proliferation and migration of cancer cells." (PMID 31752198, 2019). "All of these results indicated that circulating ZFAS1 had a relatively moderate accuracy when distinguishing gastric cancer patients from other individuals." (PMID 30288832, 2019). "The expression of long noncoding RNA ZFAS1 is up-regulated in the serum of patients with gastric cancer, in whom exosomes can promote the proliferation and migration of gastric cancer cells by transmitting the ZFAS1." (PMID 29552328, 2018). "The lncRNA ZFAS1 promotes the proliferation and migration of gastric cancer cells via the transmission of the exocrine." (PMID 29552328, 2018). "Subsequent studies also demonstrated that ZFAS1 expression is upregulated in many human malignancies, including glioma, lung, colon, liver, ovary and gastric cancers, but downregulated in breast cancer." (PMID 30186041, 2018). "Knockdown of ZFAS1 impaired gastric cancer cells proliferation and induced apoptosis in vitro, and inhibited tumorigenicity of gastric cancer cells in vivo." (PMID 27246976, 2017). "Further investigations determined that tumor suppressors NKD2 and KLF2 are novel ZFAS1 targets in gastric cancer cells." (PMID 27246976, 2017). "Validation in an cohort of 54 pairs gastric cancer and normal tissues revealed that ZFAS1 is upregulated in gastric cancer tissues and correlated with poor prognosis and shorter survival." (PMID 27246976, 2017). "Taken together, our findings illuminate how ZFAS1 over-expression confers an oncogenic function in gastric cancer." (PMID 27246976, 2017). "Higher expression of long non-coding RNA ZFAS1 is correlated with epithelial-mesenchymal transition (EMT) property of gastric cancer." (PMID 29221147, 2017). "Knockdown of ZFAS1 impaired gastric cancer cells growth and induced cell apoptosis in vitro and inhibited tumorigenesis of gastric cancer cells in vivo." (PMID 27246976, 2017). "Mechanistically, ZFAS1 was found to promote gastric cancer cell proliferation by inhibiting KLF2 and NKD2 expression." (PMID 28938617, 2017). "LncRNA ZFAS1 had been reported to be up-regulated in breast cancer, gastric cancer and hepatocellular carcinoma." (PMID 29262629, 2017). "In gastric cancer, knockdown of ZFAS1 exerts tumor-suppressive functions through reducing cell proliferation and inducing cell apoptosis." (PMID 29163829, 2017). "In this study, we identified ZFAS1, a frequently amplified lncRNA, as an oncogenic lncRNA in gastric cancer by analyzing microarray data from GEO." (PMID 27246976, 2017). "In vitro experiments also showed that gastric cancer cell proliferation decreased and apoptosis increased after ZFAS1 knockdown." (PMID 28938617, 2017). "Next, we conducted a Kaplan–Meier survival analysis to explore the correlation between ZFAS1 expression and gastric cancer patients' prognosis." (PMID 27246976, 2017). "In this study, we found that ZFAS1 expression is upregulated in gastric cancer tissue and cell lines by analyzing publicly available microarray data from GEO and validating in an cohort of 54 pairs tissue samples." (PMID 27246976, 2017). "The expression of ZFAS1 in gastric cancer tissue was also found to be significantly higher than that of para-carcinoma tissue, and its high expression was significantly related to poor overall patient survival." (PMID 28938617, 2017). "To validate the analysis finding, we detected ZFAS1 expression in an cohort of 54 pair gastric cancer and normal tissues, and 5 gastric cancer cell lines." (PMID 27246976, 2017).
gastric cancer (continued). "Aberrant high expression of ZFAS1 was reported in a series of human cancers, including hepatocellular carcinoma, gastric cancer, melanoma, lung cancer, glioma and colorectal cancer." (PMID 29137442, 2017). "The results indicated that ZFAS1 expression level had a significant predictive value for gastric cancer, and the AUC value for discriminating GC patients from healthy controls was 0.760." (PMID 27654478, 2016). "The knockdown of ZFAS1 via siRNA in gastric-cancer cell lines results in decreased cell migration, invasion, and proliferation, providing evidence that ZFAS1 may serve as an independent prognostic biomarker as well as a therapeutic target in gastric cancer." (PMID 38542354, 2024). "Furthermore, it was demonstrated that ZFAS1 RNA transmitted to gastric cancer cells directly enhanced cell proliferation and migration and was associated with the lymphatic metastasis and TNM stages." (PMID 39682778, 2024). "For instance, it was demonstrated that overexpression of ZFAS1 could enhance gastric cancer cells tumor growth in vivo." (PMID 35112985, 2022). "Previous studies revealed that ZFAS1 participated in gastric cancer cell function." (PMID 35112985, 2022). "ZFAS1 levels are higher in gastric cancer compared to para-carcinoma tissue." (PMID 35582574, 2019). "For example, in glioma and gastric cancers, the upregulation of ZFAS1 could enhance the epithelial mesenchymal transition (EMT)." (PMID 31781169, 2019). "In addition, with high diagnostic sensitivity and specificity (80.0% and 75.7%), exosomal ZFAS1 is a promising biomarker for gastric cancer diagnosis." (PMID 31360701, 2019). "In addition, suppression of ZFAS1 in gastric cancer cells increases gastric cancer sensitivity to cis-platinum." (PMID 35582574, 2019). "Exosomal ZFAS1 can increase the proliferation and invasion of gastric cancer cells." (PMID 29552328, 2018). "With regards to function, ZFAS1 has been shown to regulate cell proliferation and migration of ovarian cancer by targeting miR-150-5p, whereas, in gastric cancer, ZFAS1 was demonstrated to accelerate cell proliferation via repressing the expression of KLF2 and NKD2." (PMID 29416676, 2018). "We have previously shown that exosomes could transfer lncRNA ZFAS1 to promote gastric cancer cell proliferation, migration and invasion." (PMID 29970131, 2018). "The study confirmed that ZFAS1 may play a role in the tumorigenesis of gastric cancer and can serve as a novel target for treating gastric cancer." (PMID 29552328, 2018). "Moreover, the dysregulated ZFAS1 expression in cancer tissues have been discovered, for example breast cancer, gastric cancer and hepatocellular carcinoma." (PMID 29262629, 2017). "Moreover, the expression of ZFAS1 has been found to correlate with patient prognosis in lung, colorectal, and gastric cancers as well as glioma." (PMID 28938617, 2017). "Our results indicated that knockdown of ZFAS1 expression could suppress gastric cancer cells tumor growth in vivo." (PMID 27246976, 2017). "The results confirmed that ZFAS1 expression is increased in gastric cancer tissues and cells." (PMID 27246976, 2017). "In this study, we globally assessed the transcriptomic differences of lncRNAs in gastric cancer using publicly available microarray data from Gene Expression Omnibus (GEO) and identified an oncogenetic lncRNA ZFAS1, which may promote gastric tumorigenesis." (PMID 27246976, 2017). "Besides, ZFAS1 has ever been demonstrated that closely affected the survival of patients with gastric cancer and could be served as a strong candidate for prognostic evaluation." (PMID 37566767, 2023). "LncRNA ZFAS1 is found to increase in the serum exosomes of GC patients with gastric cancer (GC), suggesting that lncRNA ZFAS1 plays a positive role in the progression of gastric cancer." (PMID 35359390, 2022).
gastric cancer (continued). "The proliferation and migration of human gastric cancer (GC) cells were induced through an autocrine induction when an overexpression of a long noncoding RNA named ZFAS1 in the circulating exosomes was observed." (PMID 36117723, 2022). "Moreover, studies revealed that ZFAS1 could promote the tumor growth of hepatocellular carcinoma and gastric cancer in vivo." (PMID 35112985, 2022). "Experiments in vivo also showed that knockdown of ZFAS1 inhibited the tumorigenic ability of gastric cancer cells, and mechanistic experiments validated that ZFAS1 could promote the proliferation of gastric cancer cells by inhibiting the expression of KLF2 and NKD2." (PMID 28938617, 2017). "Importantly, it was shown that the transfer of exosomes from ZFAS1 high expression to ZFAS1 low expression gastric cancer cells lead to increased expression of ZFAS1 in the low expression cells, a decrease in epithelial markers and an increase in mesenchymal markers." (PMID 28430163, 2017). "Moreover, we conducted rescue assays to determine whether KLF2 and NKD2 involved in ZFAS1 contributions to gastric cancer cell proliferation." (PMID 27246976, 2017). "In GC cells, a previous study found that long non-coding RNA ZFAS1 promoted gastric cancer cells proliferation by epigenetically repressing KLF2 and NKD2 expression." (PMID 29113337, 2017). "Furthermore, we found the correlation between the ZFAS1 level and the clinicopathological characteristics of the 66 gastric cancer patients and found that the expression level of ZFAS1 is positively correlated to the TNM stage, cancer invasion, lymph node metastasis and cancer diameter." (PMID 27654478, 2016). "ZFAS1 may act as a marker for gastric cancer diagnosis, and a marker for EMT and CTCs." (PMID 27654478, 2016). "In addition, silencing of ZFAS1 could induce the apoptosis of gastric cancer cells." (PMID 35112985, 2022). "In gastric cancer (GC), ZFAS1 plays an oncogenic role by interacting with EZH2." (PMID 34249125, 2021). "Similar to the recent studies demonstrating the oncogenic role of ZFAS1 in NSCLC, HCC, gastric cancer, and other cancers." (PMID 32443980, 2020). "ZNFX1 antisense RNA 1 (ZFAS1) lncRNA is aberrantly overexpressed and is reported as an oncogene in various tumors as melanoma, ESCC, NSCLC, gastric cancer, colon cancer." (PMID 31003545, 2019). "Since this initial finding, ZFAS1 has been shown to be pro-tumourigenic and promote EMT in a number of other cancers, including colon cancer, gastric carcinoma, and glioma." (PMID 29701689, 2018). "To further determine whether KLF2 and NKD2 is involved in the ZFAS1 induced promotion of gastric cancer cells proliferation, we detected their expression in 20 pairs gastric cancer and normal tissues and found that their expression are both decreased in gastric cancer tissues." (PMID 27246976, 2017). "Furthermore, ZFAS1 expression is also overexpressed in gastric cancer, and its increased level is correlated with a shorter survival and poor prognosis and promotes the proliferation of gastric cancer cells by epigenetically repressing the KLF2 and NKD2 expression levels." (PMID 28154416, 2017). "Zinc finger antisense 1(ZFAS1), a newly identified lncRNA, has been reported to be dysregulated in multiple human cancer types including CRC, breast cancer, and gastric cancer." (PMID 28108736, 2017). "Therefore, we speculate that ZFAS1 may function as an important oncogene in gastric cancer." (PMID 27246976, 2017). "Finally, we tested whether ZFAS1 could be used as a marker of gastric cancer." (PMID 27654478, 2016). "ZFAS1 knockdown inhibited cell cycle progression, induced apoptosis, and suppressed epithelial-interstitial transformation EMT, which overall attenuated the proliferation and migration of gastric cancer cells." (PMID 35089117, 2022).
gastric cancer (continued). "LncRNA ZFAS1 (ZNFX1 antisense RNA 1), located on chromosome 20q13, abnormally expressed in a variety of cancers including breast cancer, hepatocellular carcinoma (HCC), gastric cancer, non-small cell lung cancer (NSCLC), etc." (PMID 33202381, 2020). "In this study, we also found that KLF2 can function as tumor suppressor and its' expression could be suppressed by ZFAS1 through recruiting EZH2 and LSD1 to its promoter region in gastric cancer cells." (PMID 27246976, 2017). "However, ZFAS1 has been shown to be pro-tumourigenic and promote EMT in a number of other cancers, including colon cancer, gastric carcinoma and glioma." (PMID 28430163, 2017). "ZNFX1 antisense RNA 1 (ZFAS1), a novel lncRNA transcribed in the antisense orientation of zinc finger NFX1‐type containing 1(ZNFX1), was found to be increased in multiple cancers, such as gastric cancer and hepatocellular carcinoma, contributing to cancer development and progression." (PMID 30288832, 2019). "As a newly identified lncRNA, zinc finger antisense 1 (ZFAS1) has been found in different cancers, including breast cancer, colorectal cancer (CRC), gastric cancer (GC) and hepatocellular carcinoma (HCC)." (PMID 29245995, 2017). "Interestingly, we found that ZFAS1 could directly bind with EZH2, LSD1 and CoREST (histone demethyltransferase of REST complex) in gastric cancer cells, which suggesting that ZFAS1 might also could regulate underlying targets at transcriptional levels." (PMID 27246976, 2017). "To determine whether ZFAS1 repressed NKD2 and KLF2 expression via interacting with EZH2 or LSD1 in gastric cancer cells, we evaluated their expression after knockdown of EZH2 and LSD1 in gastric cancer cells." (PMID 27246976, 2017).